CD4 (CD4 molecule)
Diseases named in the same sentence as CD4 in open-access papers (continued):
Sharing a sentence is not in itself a finding about the gene and the disease.
Sepsis (continued). "Additionally, ferroptosis has also been identified in immune cells, including CD4 T cells, macrophages, and dendrite cells during sepsis." (PMID 40715082, 2025). "In addition, the frequency of a Vα7.2+ CD4+ CD161− cluster was reduced in sepsis compared with healthy donors." (PMID 40041474, 2025). "Recent animal studies utilizing the classic cecal ligation and puncture-induced sepsis mouse model have revealed that sepsis begins at an early stage, marked by apoptosis of splenocytes, a reduction in CD4+ and CD8+ T cells, and elevated PD-L1 expression on myeloid-derived suppressor cells (MDSCs)." (PMID 40386708, 2025). "Notably, sepsis impairs the CD4+ T cell recall response and post-septic CD4+ T cells are highly glycolytic and exhibit a Th17 phenotype." (PMID 40364841, 2025). "Given the functional interdependence between apoptosis and PANoptosis in the development of sepsis, we hypothesized that ribophagy might exert modulatory effects on CD4+ T lymphocyte PANoptosis." (PMID 40995563, 2025). "Moreover, the proportions of the remaining 24 immune cells, excluding effector memory CD4+ T cells, eosinophils, monocytes, and natural killer cells, varied between the sepsis and control groups." (PMID 40274894, 2025). "In addition, Xuebijing injection was shown to increase the proportion of Th1 cells and increase the percentage of CD4+CD25+ cells, thereby regulating the immune response and reversing sepsis-associated immunosuppression." (PMID 41194878, 2025). "It was found that sepsis induced marked ribosome collisions in CD4+ T lymphocytes, which aligned with previous studies indicating that ribosome dynamics could exert dual effects as both cGAS co-activators and autophagy inducers." (PMID 40995563, 2025). "Indeed, reduced memory B cells in sepsis patients contribute to immunosuppression, and impaired CD4+ T cell memory responses have been observed in preclinical sepsis models." (PMID 41124072, 2025). "We hypothesize that decreased JAK-STAT1/2 and NFκB STP activity in whole blood of sepsis patients reflects upregulation of an immunosuppressive CD4+ T cell population such as Th2 cells, as has been suggested before." (PMID 39996782, 2025). "The proportion of CD4+ FOXP3+ T cells is elevated in sepsis patients." (PMID 41158471, 2025). "Furthermore, measurement of CD4+ T lymphocyte counts is a promising independent prognostic marker for sepsis patients." (PMID 39290582, 2024). "It counteracts sepsis-induced apoptosis in CD4+ T cells, which weakens defense mechanisms against pathogens, exacerbates bacterial dissemination, and intensifies inflammation, thereby accelerating sepsis progression." (PMID 39726955, 2024). "Compared to individuals not subjected to this factor, those exposed to CD4 Treg AC have a marginally elevated sepsis risk by approximately 0.08%." (PMID 39465765, 2024). "Human patients and experimental mouse models of sepsis exhibit profound CD4+ T-cell apoptosis." (PMID 39290582, 2024). "Additionally, our analysis of intercellular communication revealed that monocytes and CD4+ T cells were crucial in the development of sepsis, notably in cases with elevated DDR levels." (PMID 38404591, 2024). "Sepsis also results in the dysfunction of CD4+ T cells due to metabolic reprogramming." (PMID 38474403, 2024). "Our study observed an obvious increase in Tregs despite a decrease in total CD4+ T cells in late-stage sepsis, indicating that NETs may facilitate communication between the adaptive and innate immune responses by interacting with Tregs." (PMID 38888975, 2024). "Then, we could draw a conclusion that mTOR deletion restore CD4+ T-cell dysfunction in sepsis through alleviating CTLA4 accumulation by easing autophagy disorder." (PMID 39104632, 2024).
Sepsis (continued). "In this section, we found that strong correlation between increased levels of DDR and heightened intercellular communication, implicating enhanced interactions, particularly among monocytes, CD4+ T cells, and DCs, as potential contributors to the severity of sepsis." (PMID 38404591, 2024). "Several previous studies have demonstrated the CD28, CD3, CD4 molecules in sepsis or septic shock." (PMID 39654893, 2024). "CD4+ T lymphocytes act as early biomarkers of sepsis and impact the prognosis." (PMID 39439897, 2024). "However, as the CD4 cell count declines, the incidence of bacterial pneumonia increases, as does the incidence of accompanying bacteremia and septicemia." (PMID 39727640, 2024). "PMN-MDSCs from late sepsis significantly inhibited the proliferation of CD4+ and CD8+ T cells, whereas CD11b+Ly6G+ cells from early sepsis could not." (PMID 38385073, 2024). "TIGIT modulates CD4+ T cell response against polymicrobial sepsis, suggesting that TIGIT could serve as a potential therapeutic target for sepsis." (PMID 38545097, 2024). "Immunoadjuvant adjunctive IFN-γ therapy, along with IL-7 and anti-PD1/PD-L1, could be beneficial for patients with sepsis, as it has proven impacts on enhancing CD4+ and CD8+ T cell functions." (PMID 39720718, 2024). "We found that the proportion of CD4 + T cells decreased in both aging and septic states by comparing E-NoSEP to Control and Y-SEP to Control separately, which is consistent with previous reports of aging-induced decreased expansion and sepsis-induced increased apoptosis in CD4 + T cells." (PMID 38909272, 2024). "Sepsis has marked effects on tissue and circulating T lymphocytes, particularly CD4+ T cells." (PMID 38474403, 2024). "However, during the late phase of sepsis, it enhanced the anti-inflammatory phenotype of macrophages and CD4+ T cells." (PMID 38576606, 2024). "In this study, TIGIT modulated CD4+ T cell immunity against bacterial infection during sepsis." (PMID 38545097, 2024). "Although the importance of the CD4+ T cell response after sepsis has been recognized for some time, other host T cells responses have not traditionally been highlighted after severe infection, specifically in regard to sepsis survivors with poor outcomes." (PMID 39691721, 2024). "Additionally, the spatiotemporal role of septic DCs reported by some studies suggests that systemic- and mucosal-derived subsets of DCs impact the proliferation of CD4 T cells differently and ultimately influence disease patterns in sepsis." (PMID 38667530, 2024). "Given the role of TIGIT in negative regulation of CD4+ T cell function in the context of acute sepsis, we determined whether TIGIT blockade could lead to similarly relieved prognosis shown in TIGIT deficient mice." (PMID 38545097, 2024). "Similarly, multivariate logistic regression analysis showed that only CD4+ T lymphocyte counts were an independent predictor of 28-day mortality in sepsis patients." (PMID 39290582, 2024). "Based on the data, it seems clear that measurement of CD4+ TFH cell frequencies in sepsis alone may be insufficient to explain a dampened ’helper’ response, and that phenotypic differences in CD4+ TFH cells could alter their overall functional capacity." (PMID 38197178, 2024). "The potential implication of an augmented quantity of circulating Tregs, specifically CD4+CD25+Foxp3+ cells, may be involved in the promotion of lymphocyte anergy and immunoparalysis linked to sepsis." (PMID 38474403, 2024). "As HIV is a condition of chronic stimulation, it is plausible that sustained activation by high antigen load in sepsis could drive similar transcriptional changes in CD4+ TFH cells, rendering them incapable of supporting B cell development." (PMID 38197178, 2024). "Thus, this study proved that miR-223 participate in the regulation of LPS-induced autophagy via the regulation of FOXO1 expression in CD4+ T lymphocytes which shed a new light for the diagnosis and treatment of sepsis." (PMID 39439897, 2024).
Sepsis (continued). "Second, in terms of adaptive immunity, researchers have found that intravenous usage of calcitriol after sepsis could modulate the homeostasis of CD4+ T-cells and reduce sepsis-induced kidney injury in obese mice." (PMID 39902186, 2024). "Nevertheless, the principal component analysis still showed that the immune potential indicators [CD4+ T-cell count, HLA-DR+ monocytes (%), and mDCs (%)] and anti-inflammatory cytokine IL-1ra were the most important variables in survived and deceased sepsis patients, respectively." (PMID 38707899, 2024). "This study investigates sepsis-induced apoptosis and its pathways, by assessing changes in PD-1 and PD-L1 serum levels, CD4+ and CD8+ T cells, and Sequential Organ Failure Assessment (SOFA) and Acute Physiology and Chronic Health Evaluation (APACHE II) severity scores." (PMID 39064603, 2024). "Our results align with this, indicating that sepsis patients exhibited a markedly reduced count of adaptive immune cells (CD4 and CD8 T cells) and innate immune cells (NK cells and DCs) compared to the control group, whereas monocytes, M1 macrophages, and neutrophils were significantly elevated." (PMID 39763654, 2024). "Distinct disparities were observed in the infiltration patterns of four immune cells types between the two groups: compared to critical control group, sepsis group had higher proportions of monocytes and activated memory CD4+ T cells, and lower proportions of resting mast cells and CD8+ T cells." (PMID 38912048, 2024). "The apoptosis or decrease of CD4+ T cells indeed assumes a crucial role in sepsis progression." (PMID 39465765, 2024). "In addition to its significant effect on CD4+T cells in sepsis, many studies have found that TIM-3 also plays an important role in the immune response of other types of T cells." (PMID 38576606, 2024). "Simultaneously, trauma and blood loss suppress the activity of T and B lymphocytes, thereby reducing the number of CD4+ T and natural killer cells and leading to low immunity, which greatly increases the probability of severe sepsis and multi‐organ system failure." (PMID 37773708, 2023). "We constructed sepsis model in mice and mouse CD4+ T and CD19+ B lymphocytes." (PMID 37636994, 2023). "Notably, a remarkable difference was found in 23 kinds of immune cells between the two sepsis subgroups, especially activated B cells, CD4+ T cells, immature dendritic cells, and plasmacytoid dendritic cells." (PMID 37346041, 2023). "According to previous studies, MALT1 is able to regulate the polarization of macrophages and CD4+ T cells; however, whether similar regulatory effects also exist under sepsis conditions is still unclear." (PMID 36960276, 2023). "Sepsis-induced persistent immune paralysis is defined, in part, by impaired CD4+ and CD8αβ+ T cell responses in the post-sepsis setting, whereas dysfunction of T cell immunity impacts naive, effector, and memory T cells, and is not restricted to classical CD8αβ+ T cells." (PMID 36768914, 2023). "Autophagy dysfunction leads to CD4+ T-cell apoptosis during sepsis." (PMID 37834169, 2023). "Consistently, the antioxidant activity, indicated by SOD and GPX activities, showed further reduction in CLP model mice treated with EVs from patients with sepsis-induced lung injury and from LPS-treated CD4+ T cells compared with EVs from control subjects and from untreated CD4+ T cells." (PMID 36959535, 2023). "Similarly, memory B cells, CD8+ T cells, CD4+ memory resting T cells, and resting NK cells were decreased in sepsis, while gamma delta T cells, monocytes, M0 macrophages, activated DCs, and resting mast cells were increased when compared to healthy controls." (PMID 37822934, 2023). "For example, the T-cell CD4 memory resting/T-cell follicular helper ratio displayed the highest positive correlation with the T-cell receptor signaling pathway (R = 0.68, P < 0.01), which was down-regulated in sepsis patients." (PMID 38053180, 2023).
Sepsis (continued). "However, multiple other studies have demonstrated a higher expression of PD‐1 in memory subsets of B cells and CD4+ T cells among individuals suffering from sepsis." (PMID 38020710, 2023). "Sepsis is also associated with T-cell depletion, and sepsis-associated CD4+ T-cell and CD8+ T-cell apoptosis led to lymphocytopenia, immunosuppression, and increased susceptibility to secondary infections in patients with advanced sepsis." (PMID 37203184, 2023). "Furthermore, we observed that inducing sepsis in mice leads to a decrease in the percentage of CD4+ T-cells, while the percentages of T helper cells (Th2 and Th17) and regulatory T-cells (Treg) are upregulated." (PMID 38028617, 2023). "Hence, high miR-93-5p levels in sepsis simultaneously suppress multiple avenues of T cell activation, mainly that of CD4+ T cells, inducing a state of anergy that is reversible by miR-93-5p inhibition." (PMID 37261908, 2023). "Interestingly, we found that T cell subsets were significantly correlated with sepsis, and the proportion of naive CD4+ T cells, memory activated CD4+ T cells, memory resting CD4+ T cells and CD8+ T cells in sepsis patients decreased significantly." (PMID 37620751, 2023). "The count of CD3+, CD4+, and CD8+ T cells and the ratio of CD4+/CD8+ in sepsis patients within 24 hours after admission to the ICU showed that most of the 206 enrolled patients had decreased T lymphocyte counts of CD3+, CD4+, and CD8+, and 45 patients (21.8%) had a decreased CD4+/CD8+ ratio." (PMID 38170088, 2023). "Moreover, we noticed that S100A9high monocytes exerted profound immunosuppressive function on CD4+ T cell immune response reminiscent of MDSCs, inhibition of which served as a potential therapeutic strategy for treating sepsis-induced immunosuppression." (PMID 37337301, 2023). "Patients with sepsis, especially severe sepsis and septic shock, had obviously higher expression levels of PD-1 on CD4+ or CD8+ T cells, PD-L1 on monocytes, sPD-1, and sPD-L1 compared with patients with non-septic infections, non-infectious inflammation, and a healthy control group." (PMID 37261359, 2023). "Previous research has indicated that increased apoptosis of CD4+, CD8+, and Th17 lymphocytes, decreased NK cells, and decreased B cells are associated with poor prognosis of sepsis, including shock and death." (PMID 37564869, 2023). "Similarly, a study examining sepsis induced by CLP also reported reduced activity of CD4+ T lymphocytes." (PMID 38193079, 2023). "Furthermore, we found similar CD4 + T-cell infiltration level trends in both m6A cluster A and gene cluster A, which helped to predict the clinical features of sepsis." (PMID 36781867, 2023). "Finally, the Wnt signaling pathway had the highest correlation with the macrophage/T-cell CD4 ratio (R = − 0.61, P < 0.01), and it was down-regulated in sepsis." (PMID 38053180, 2023). "Within the CD4+ T cell pool, we further noted a sepsis-specific decrease in CD4+ central memory T (Tcm) cells (anti–miR-93-5p vs. sham: P < 0.001, scrambled control vs. sham: P < 0.01; anti–miR-93-5p vs. control: P < 0.01, scrambled control vs. control: P < 0.01)." (PMID 37261908, 2023). "Therefore, aside from the functional exhaustion of T cells in the later stage of sepsis, the drastic reduction of CD4+ T cell numbers would attribute to the first hit of systemic hyperinflammation of sepsis." (PMID 37332010, 2023). "Most of SCAP combines with sepsis‐related immunosuppression, and CD4+ T cells decrease may due to proliferation and apoptosis." (PMID 37773700, 2023). "In advanced sepsis, the number and function of various peripheral immune cells, including CD4 + T cells, CD8 + T cells, B cells, and natural killer cell, may be affected, resulting in the inability of the immune system to effectively eliminate pathogens." (PMID 37330481, 2023). "In sepsis the number of CD4+ helper cells are greatly reduced following disease onset." (PMID 37946314, 2023).
Sepsis (continued). "In addition, with the inhibition of Th1/Th2/Th17 cytokines produced by CD4+ T cells, the phagocytotic ability of macrophages decreased, and the ability of the spleen to clear bacteria was inhibited after sepsis." (PMID 36873283, 2023). "The mechanisms of sepsis‐induced immunosuppression include apoptosis depletion of immune cells, increased expression of negative costimulatory molecules, increased expression of regulatory T cells (Tregs) and programmed cell death of CD4+ T cells." (PMID 37060578, 2023). "In terms of adaptive immunity, sepsis-induced apoptosis leads to lymphocytopenia in patients with SS, and this process involves all types of T cells, including T regulatory cells, CD4 + T cells, CD8 + T cells, and natural killer cells, which are conducive to immunosuppression." (PMID 37575977, 2023). "An increase of the proportion of CD3+CD4+ T cells in sepsis was observed in some septic patients where they could represent up to 50% of total PBMCs." (PMID 38094297, 2023). "In sepsis, CD4+ T-helper cells, specifically Th1, Th2, and Th17 cells, are suppressed." (PMID 37681852, 2023). "This indicates that mTOR is activated by ERS to affect CD4+ T cell apoptosis during sepsis." (PMID 35915740, 2022). "The GATA3 SNP rs3824662 may have also contributed to the apoptosis of CD4+ T cells in the onset of sepsis, accelerating the progress of sepsis." (PMID 36714653, 2022). "We used this model to investigate whether mTOR could be pharmacologically used to regulate CD4+ T cell apoptosis thereby enhancing the immunity and improving the prognosis of patients with sepsis." (PMID 35915740, 2022). "CD4 + cells in patients with sepsis have an increased expression of inhibitory receptors, including PD-1, 2B4, BTLA, and TRAIL, which could lead to a weakened immune response." (PMID 35910903, 2022). "The proportions of plasma cells, T cells CD4 memory activated, and some innate cells in the sepsis group were significantly higher than those in the healthy group, while the proportions of T cells CD8, T cells CD4 memory resting, T cells regulatory (Tregs), and NK cells were lower." (PMID 36250055, 2022). "On the basis of these results, we hypothesized that the mTOR pathway may also play a vital role in A-L fusion failure in CD4 + T cells during sepsis." (PMID 35435531, 2022). "In addition to the PD-1 and PD-L1 axes, TIM-3 expression is significantly increased on CD4+ T cells in patients with sepsis." (PMID 36209190, 2022). "Moreover, in a murine model of sepsis, administration of miR-181d mimics decreased CD4+ and CD8+ T cells in spleen and lymph nodes and reduced the TNF-α levels in serum." (PMID 35432384, 2022). "This suggests that the functional status of CD4+ T cells is closely related to severity of sepsis." (PMID 35898496, 2022). "GM-CSF therapy in sepsis patients leads to a significant decrease in CD4+FOXP3+ Tregs." (PMID 35720398, 2022). "This also suggests that infiltration of macrophages could inhibit lung tissue-specific CD4+CD25+Foxp3+ Tregs via HMGB1/PTEN/β-catenin axis in sepsis-induced ALI." (PMID 35281010, 2022). "MDSCs increased FOXP3 expression on CD4+ T cells in sepsis patients (p = 0.006)." (PMID 35720398, 2022). "This indicates that mTOR participates in and regulates ROS-mediated ERS-related CD4+ T cell apoptosis in sepsis, raising the possibility of mTOR becoming a new targeted treatment strategy for alleviating CD4+ T cell apoptosis and improving the immune status of those experiencing sepsis." (PMID 35915740, 2022). "Additionally, it is illustrated that MALT1 enhances the differentiation of CD4+ T cells into Th1 and Th17 cells, meanwhile the differentiation of CD4+ T cells into Th1 and Th17, which are important in the pathology of sepsis." (PMID 35262976, 2022).